TNF (tumor necrosis factor)
Diseases named in the same sentence as TNF in open-access papers (continued):
Sharing a sentence is not in itself a finding about the gene and the disease.
colitis (continued). "Coinciding with the data obtained from the current work, DSS administration was reported an increase caspase-8 levels, which, consequently, enhances TNF-α induced an epithelial necroptosis and promotes the development of colitis." (PMID 35631426, 2022). "The maximum inflammatory response was found in the DSS-induced colitis model, as shown by higher detected levels (p < 0.05) of IL-6, TNF-α, IFN-γ, and IL-10 cytokines." (PMID 35884960, 2022). "GrTP showed a similar efficacy to sulfasalazine in reducing inflammatory markers (TNFα, IL-6 and serum amyloid A), restoring concentrations of antioxidant agents (glutathione and cysteine) and attenuating colitis in murine models of both UC and CD." (PMID 35407131, 2022). "Meanwhile, TNF-α, IL-6, and IL-1, proinflammatory cytokines, are crucial in the development of colitis." (PMID 36500439, 2022). "In another study conducted on dextran-sodium-sulfate (DSS)-induced colitis in rats, the effects of neem leaf extracts on the levels of IL-6 and TNF-α were evaluated." (PMID 36145202, 2022). "Butyrate treatment improves transepithelial resistance in a Dextran Sulfate Sodium-induced colitis rat model, which is related to maintaining tight junction integrity and inhibiting tumor necrosis factor (TNF)-α release." (PMID 36186124, 2022). "TNFα, as an important pro-inflammatory factor in ulcerative colitis, plays an important role in the occurrence and development of colon inflammation." (PMID 36064365, 2022). "In contrast, the levels of TNF-α, IL-6, and IL-1β were increased considerably, indicating that colon inflammation was induced in mice after DSS treatment." (PMID 36359970, 2022). "While both studies demonstrated significant improvement of ICB efficacy in melanoma with reduced ICB-installed colitis, we were unable to show any added benefit of TNF-α and PD-L1 co-blockade." (PMID 35493461, 2022). "In vivo murine studies revealed that KJK exposure increases the body weight and colon length, while reducing colonic epithelial injury, and the expression of inflammatory factors in colitis tissues such as TNF-α, IL-6, and IL-1β." (PMID 35774753, 2022). "This study provides the rationale for the possible innovative use of penfluridol as a newly identified small-molecule drug for TNFα-driven diseases, such as inflammatory arthritis and colitis." (PMID 35045889, 2022). "Our present study indicates that rapamycin-induced autophagy significantly alleviates experimental colitis and decreases the TNF-α secretion from LPS-induced HT-29 cells, which were in accordance with the previous studies." (PMID 36032781, 2022). "In a dinitrobenzene sulfonic acid-induced colitis model, guanosine lowered IL-1β, IL-6, and TNF-α mRNA levels and downregulated the expression of NF-κB p65 and the levels of ROS and nitrite." (PMID 36235070, 2022). "The results showed that, compared with the control group, the levels and expression of pro-inflammatory factors TNF-α, IL-1β, and IL-6 in colon tissues from colitis mice were significantly increased." (PMID 35387334, 2022). "We used 2% DSS colitis and TNF-α challenged HT-29 adenocarcinoma cells as in vivo and in vitro models." (PMID 36557879, 2022). "Since TNF blockade affected not only colonic IL-22BP expression, but also its serum levels in the humanized mouse, TNF-dependent colitis model, we next quantified human IL22-BP in IBD patients." (PMID 35383266, 2022). "Correspondingly, the expression levels of TNF-α and IL-6, which were secreted by macrophages, were significantly decreased in the plasma of colon cancer and colitis mice after injection of HUC-MSCs." (PMID 35694239, 2022). "First of all, the JW formula efficaciously alleviated the inflammatory reactions during the progression of colitis, as evidenced by the decreased IL-1b and TNFα levels in the serum of colitis mice after the JW therapy." (PMID 36091591, 2022).
colitis (continued). "Together, these data reveal that PD suppresses the infiltration of macrophages by inhibiting MMP-7 and the production of TNF-α in the DSS-induced colitis mouse model." (PMID 35933374, 2022). "The mass accumulation of IL-6, IL-1β and TNF-α is one of the features of DSS-induced colitis, which amplifies the inflammatory cascades and accelerates the disease progression." (PMID 35211182, 2022). "As typical indicators of infDCs, the inhibition of TNF-α+ DCs, E-cadherin+ DCs, and pro-inflammatory cytokines in colitis mice has been considered a potential therapeutic target." (PMID 36310616, 2022). "Overexpression of NF-κB induces the hyperactivation of inflammatory response and promotes the release of proinflammatory cytokines (containing TNF-α, IL-6, and IL-1β), even facilitating the occurrence of colitis." (PMID 35681301, 2022). "This leads to the activation of NF-κB signaling and the expression of pro-inflammatory cytokines such as TNFα and IL-6, in the in vivo mouse model of colitis." (PMID 34983535, 2022). "In colitis models, oral uptake of these particles decreased the pro-inflammatory cytokines (TNF-α, IL-6, and IL-1), raised the anti-inflammatory cytokines (IL-10 and IL-22), and was shown to be a preventive therapy against colitis-related malignancy." (PMID 36298592, 2022). "In the present study, we observed that plasma TNF-α, IL-6, and IL-17 were significantly increased in mice with colitis." (PMID 36009796, 2022). "In the colons of TNBS-induced colitis mice, BS reduced the expression of proinflammatory cytokines TNF-α, IL-1, and IL-6, as well as COX-2 and activation of NF-kB." (PMID 35990343, 2022). "Rapamycin protects against colitis through induction of autophagy, thus inhibiting the activation of NF-κB pathway and secretion of TNF-α." (PMID 36032781, 2022). "Treatment with CM in TNBS-induced colitis in rats also resulted in a reduced levels of colonic TNF-α and IL-10." (PMID 35493477, 2022). "TNF-α, IL-6, IL-1β, and IL-2 are involved in many inflammatory visceral pain diseases like visceral pain after colitis, surgery, and endometriosis." (PMID 35642022, 2022). "Blocking RIPK1 by Nec-1s in vivo (DSS-induced colitis in mice) and in vitro (TNF-α induced inflammation in the IEC cell line) dramatically alleviated the colitis and cell death which shares the same phenotype with ABIN1 overexpression." (PMID 36034412, 2022). "Lactobacillus acidophilus treatment can also alleviate the severity of DSS-induced colitis and inhibit pro-inflammatory cytokines in the colon, such as IL-1β、 IL-6、IL-17, and TNF-α." (PMID 36189293, 2022). "Anti-TNF-alpha drugs have shown success in treating uveitis, colitis, and hepatitis in steroid-resistant irAEs." (PMID 35744922, 2022). "In LPS-treated HT-29 cells and TNBS-induced colitis, p65 is overexpressed, which results in exaggerated secretion of TNF-α and induce or worsen the inflammation in the bowel." (PMID 36032781, 2022). "In line with our findings, the authors showed that IRAK-M plays a key role in downregulating the induction and progression of DSS colitis through the modulation of proinflammatory cytokines such as TNF-α and IL-6." (PMID 35495925, 2022). "B. vulgatus 7K1 ameliorated DSS-induced colitis in mice by decreasing the concentrations of TNF-α and IL-6 and increasing the production of IL-10 in mouse colon tissues." (PMID 36531989, 2022). "In colitis mouse models, treatment with cocoa-derived polyphenols resulted in a considerable decrease in TNF-α and IL-1 levels in the inflamed colon." (PMID 36235770, 2022). "In the present study, we investigated the role of rapamycin on the expression of NF-κB p65 and TNF-α in TNBS-induced mouse colitis and LPS-induced HT-29 cells." (PMID 36032781, 2022). "Compared with wild-type mice, SIGNR3−/− mice exhibited more severe symptoms of colitis accompanied by a significant increase of TNF-α." (PMID 36084127, 2022).
colitis (continued). "Expression of TNF-α was measured, and histopathological examinations were performed to assess colon inflammation in IBS-D model rats." (PMID 36210803, 2022). "The study indicated that, a large number of proinflammatory factors (IFN-γ, IL-1β, IL-6, and TNF-α) were produced in the serum and colonic tissues after colitis was induced by DSS in mice, while the anti-inflammatory factors (IL-10 and IL-4) decreased." (PMID 36159803, 2022). "Mice treated with carvacrol had decreased TNF-α levels and milder lesions following acetic acid-induced colitis." (PMID 36139216, 2022). "Konjac oligosaccharide can decrease the levels of malondialdehyde, inducible nitric oxide synthase, TNF-α, and IL-1β in colonic tissues of rats with colitis, and has significant anti-inflammatory effects." (PMID 36033869, 2022). "It was remarkable that rats that suffered from DSS-induced colitis had the highest expression levels of pro-inflammatory cytokines IL-6, IL-1β and TNF-α and anti-inflammatory IL-10 levels." (PMID 35745756, 2022). "In this study, we preliminarily confirmed that co-administration of L. gasseri KBL697 and IFX, a commercialized TNF-α inhibitor, can significantly alleviate colitis symptoms in the DSS-induced colitis mouse model." (PMID 35688918, 2022). "In the DSS-induced colitis, reduced weight was recovered and a decrease in inflammatory factors Ig-E and TNF-α in the mesenteric lymph node (MLN) and spleen was induced, and it was confirmed to help with the morphological remodeling of the intestine." (PMID 35897919, 2022). "Further studies uncovered that PYY 3–36 treatment reduced the levels of colon myeloperoxidase (MPO) and both colonic and systemic TNF-α and IL-6 observed in murine colitis." (PMID 35443853, 2022). "Despite being both forms of TNF detrimental for the course of colitis, the expression of mTNF by CD14 + macrophages has been reported to be relevant in IBD17, and mTNF signaling has been implicated in the development of granulomas in CD patients." (PMID 35705557, 2022). "Studies in animal models of acute colitis showed increased hippocampal excitability, that was dependent on microglial activation and mediated by TNF-α, together with increased excitatory glutamatergic transmission." (PMID 35628158, 2022). "In the acute DSS-induced mice colitis model, EA attenuated colitis severity slightly through the reduction of inflammatory mediators (IL-6, TNF-α, and IFN-γ)." (PMID 35805952, 2022). "Recent studies suggest that high levels of pro-inflammatory cytokines, including IFNγ, TNFα, IL1β, IL6, and MCP1, are implicated in DSS-induced colitis." (PMID 35888062, 2022). "Biopsies of inflamed colon mucosa from patients with IBD exhibited increased LTA and IL1B expression, including a subset of patients with active colitis on anti-TNF therapy." (PMID 35077396, 2022). "Levels of the pro-inflammatory cytokines, TNF-α and interleukin-1b (IL-1b) in the colonic tissue were significantly elevated in both colitis control groups (CTRL+, BSA-NP) compared to untreated control (CTRL–)." (PMID 35214083, 2022). "A recent study in patients with melanoma treated with combined immune checkpoint blockade (CICB) targeting CTLA-4 and PD-1 who developed ≥ grade 3 colitis demonstrates an intestinal overexpression of IL1β and TNF compared to normal tissue." (PMID 35432346, 2022). "In spite of this, SM934 regulated the balanced Bcl-2 and BAX, and cleaved caspase-9 and cleaved caspase-3 in colitis, and also downregulated the cleaved caspase-3 in TNF-α-induced IEC apoptosis in vitro." (PMID 36120344, 2022). "Further, naïve‐HA and HA‐enema treatment reduced serum inflammatory markers (IL‐6, TNF‐α) compared to vehicle in DSS‐induced colitis mice." (PMID 34761543, 2022). "IrAEs associated with ICIs can be treated with corticosteroids in most cases or tumor necrosis factor-α (TNFα) inhibitors in certain toxicities such as colitis." (PMID 35330111, 2022).
colitis (continued). "A prior study suggested that the elevation of colonic TNF-α, IL-6, and IL-1β levels in colitis mice were induced by DSS, which is consistent with our findings." (PMID 35681301, 2022). "To further dissect the mechanism of how TNF controls IL-22BP expression during colitis, we quantified human and murine TNF protein levels in ex vivo colonic explants upon TNF ablation." (PMID 35383266, 2022). "Dietary arginine and glutamine have significantly decreased colonic IL-17 and TNF-α cytokines in a dextran sulfate sodium-induced colitis mice model." (PMID 35938108, 2022). "On the other hand, IRAK3 knockout mice stimulated using colitis-induced model show significantly increased mRNA and protein expression of TNF-α and IL-6 compared to IRAK3 wild type mice." (PMID 35167625, 2022). "The results of established colitis treatment showed that the neutralization of TNF-α by the antibody generated a reduction in CD68 and myeloperoxidase (MPO) markers, indicating a reduction in macrophages and neutrophils in the colon tissue." (PMID 35939430, 2022). "Injection of anethole at doses of 31.25 (P < 0.001), 62.5 (P < 0.05), 125 (P < 0.001), and 250 mg/kg (P < 0.001) meaningfully reduced the expression of TNF-α in relationship to the colitis (saline-treated) group." (PMID 35432569, 2022). "TNF-α blockade has been used to treat certain irAEs resulting from CPIs, such as colitis, which shares activation of TNF and IFN-γ pathways." (PMID 35925682, 2022). "The acute inflammatory response that occurs in mice with DDS-induced colitis is at least partially related to the overexpression of the inflammatory cytokines IL-1β, IL-6, and TNF-α." (PMID 36431883, 2022). "EVs from mouse BMSCs primed with a cocktail of cytokines (IL-1β, IL-6 and TNF-α) had higher efficacy in reducing the necrotic mucosal surface and collagen deposition in a dextran sulfate sodium-induced colitis model." (PMID 36341339, 2022). "B. bifidum BGN4-SK significantly ameliorated the symptoms of DSS-induced colitis, increased the expression of tight junction genes (claudin and ZO-1), and decreased pro-inflammatory cytokines IL-6, IL-1β and TNF-α." (PMID 35672695, 2022). "Administration of montelukast (20 mg/kg, i.p.)produced a significant attenuation (p < 0.05) in the levels of the TNF-α and IL-1β in acetic acid-induced colitis." (PMID 36225573, 2022). "Current therapeutic guidelines for checkpoint blockade-induced colitis include corticosteroids and, if the patient is refractory to steroids, immunomodulating antibodies, such as anti-TNF and anti-integrin agents." (PMID 36612082, 2022). "More research is required regarding the duration of therapy of TNF-alpha blockers and the management of colitis refractory to TNF-alpha blockers." (PMID 35453540, 2022). "In the animal models, including TNBS and DSS-induced colitis, TNF-α was also significantly upregulated." (PMID 35847065, 2022). "To address this gap, we investigated the effects of co-administration of Lactobacillus gasseri (L. gasseri) KBL697 and infliximab (IFX), the first approved tumor necrosis factor (TNF)-alpha inhibitor, on the dextran sodium sulfate-induced colitis mouse model." (PMID 35688918, 2022). "Similar to human patients, murine colitis models show intense accumulation of Ly6Chi monocytes, which also produce high levels of IL-1β, TNF-α, IL-6, IL-12, and express high level of TREM1 and respond in a highly pro-inflammatory manner to TLR stimulation." (PMID 34912006, 2022). "In vitro, EsA treatment increased the number of DSS-inhibited bowel movements and body weight, improved the histological score of colitis, and inhibited the inflammatory response by reducing IL-6 and TNF-α levels in rats." (PMID 36091585, 2022). "Regarding the molecular mechanism, PE-EPS reduced the enhanced expression of inducible nitric oxide synthase (iNOS), cyclooxygenase-2 (COX-2), and pro-inflammatory cytokines (TNF-α, IL-6, and IL-1) in the colon tissue of colitis-induced mice." (PMID 36080669, 2022).
colitis (continued). "Various cytokines play important roles in colitis, in which IL-1β and TNF-α are important inflammatory cytokines and were expressed abundantly during the period of colitis." (PMID 36499169, 2022). "In the fully “humanized TNF” colitis model, when naive T cells from hTNF-KI mice were transferred into hTNF-KI×Rag1−/− recipients, chronic autoimmune colitis developed." (PMID 35383266, 2022). "In steroid-resistant irAEs, anti-TNF-alpha agents have displayed efficacy in controlling uveitis, colitis and hepatitis." (PMID 35392134, 2022). "T-bet deficiency within the innate immune compartment results in spontaneous colitis triggered by Helicobacter typhlonius, which drives excess TNF-α production and promotes colitis in Tbx21−/−Rag2−/− ulcerative colitis (TRUC) mice." (PMID 35163778, 2022). "Further, the bovine and human MDEs attenuated the mucosal lesions, lymphocyte infiltration, colon shortening, and gene expression of pro-inflammatory cytokines (IL-6, TNF-α) in the DSS-colitis mice." (PMID 35399093, 2022). "Our in vivo studies showed that apigenin inhibited TNF-α, IL-6, and IL-1β secretions in colitis of DSS-induced mice." (PMID 36590200, 2022). "Despite the plethora of data on the action of TNF on various target cells, the precise in vivo action of TNF during active colitis remains scarce." (PMID 35383266, 2022). "TNF-α is another essential proinflammatory cytokine secreted by macrophages and lymphocytes during colitis that plays a role in activating inflammatory nuclear transcription factors." (PMID 35126813, 2022). "In vivo, DPG decreases the severity of DSS-induced colitis as well as intestinal inflammation reduction mediated by a downregulation of the pro-inflammatory cytokines TNF-α, IL-1β, and IL-6, as well as HMGB1 receptors, RAGE, and TLR4." (PMID 35456938, 2022). "HHT alleviated DSS-induced colitis with downregulated TNF-α, IL-1β, IL-6, and CCL2 expression; reduced activation of nuclear factor-kappa B (NF-κB) signaling; and diminished proportion of recruited macrophages in colon tissues." (PMID 36211988, 2022). "TNBS colitis mice showed elevated levels of TNF-α and treatment groups showed a remarkable decrease in their level." (PMID 35565934, 2022). "Data presented so far revealed that T cell-derived TNF controls IL-22 mediated epithelial restitution during colitis in the humanized TNF mouse model." (PMID 35383266, 2022). "The study revealed a high potency of (HT) in suppressing inflammation and alleviating colitis symptoms via downregulation of IL-6, IL-1β, TNF-α, and myeloperoxidase enzyme." (PMID 35990343, 2022). "Similar results were obtained in a DSS mouse model (129 3/SvImJ) of colitis; TNF-α inhibition (etanercept or XPro1595) improved colonic contractile activity." (PMID 35805922, 2022). "In DSS colitis, macrophages from RELMβ–/– mice exhibited lower levels of TNF‐α and IL‐15 production, resulting in mice more resistant to intestinal inflammation." (PMID 35593111, 2022). "D-limonene demonstrated anti-inflammatory effects in colitis by decreasing cytokines (NF-κB, TNF-α, IL-1β, and IL-6) when administered orally in rats." (PMID 36432834, 2022). "With this background, we investigated the actions of FREG on protecting the barrier function in TNBS induced colitis rats and TNF-alpha induced human intestinal Caco-2 cells." (PMID 35130890, 2022). "Combined treatment reduced colitis inflammation by neutralizing TNF-α and blocking TNFR1, down-regulating colonic expression of TNF-α by disrupting positive feedback and the gene expression of IL-1β and IL-8 in peritoneal macrophages." (PMID 35939430, 2022). "Compared with the control group, the level of TNF-α production in the TNBS-induced colitis group was significantly increased, but this pathogenically increase were reversed by the treatment of RSBDP." (PMID 36034874, 2022).